RNU6-1294P (RNA, U6 small nuclear 1294, pseudogene)
Gene: Small nuclear RNA gene on chromosome 3 (142,407,657 to 142,407,737, reverse strand). Ensembl gene ENSG00000251804.
Homologues: Orthologues: macaque U6 (96% identical), pig U6 (79% identical), mouse Gm55140 (67% identical), rat LOC120093923 (67% identical), mouse Gm55125 (65% identical), mouse Gm56276 (64% identical), guinea pig U6 (62% identical). Paralogues in human: RNU6-744P (88% identical), RNU6-797P (88% identical), RNU6-1209P (86% identical), RNU6-931P (86% identical), RNU6-1091P (85% identical), RNU6-1145P (85% identical), RNU6-1175P (85% identical), RNU6-1287P (85% identical), RNU6-1311P (85% identical), RNU6-23P (85% identical), RNU6-445P (85% identical), RNU6-560P (85% identical), and 1283 more.